IL6 (interleukin 6)
Diseases named in the same sentence as IL6 in open-access papers (continued):
Sharing a sentence is not in itself a finding about the gene and the disease.
silicosis (continued). "In AMs from observers and silicosis patients, we found that the concentrations of IL-1β, IL-6, and TNF-α were significantly higher in the presence of LPS than those in the absence of LPS (P < 0.01)." (PMID 33817248, 2020). "This suggests a milieu distinct from that described in silicosis, in which IL6 and TNF-α levels are typically increased." (PMID 31632407, 2019). "In the experimental silicosis model, IL-6 activities in the sera and in the culture supernatants of pulmonary fibroblasts were also inhibited by it." (PMID 18475741, 1996). "Moreover, the expression of silicosis related cytokines (IL-1β, IL-6, TNF-α, and TGF-β1) in BALF was further detected using ELISA." (PMID 39060930, 2024). "In human plasma/serum, TNF-α levels in patients with silicosis or IL-1β, IL-6 and TNF-α in CWP patients have also been reported to be increased compared to control groups and even between simple pneumoconiosis and PMF groups, in accordance with the results in the present study." (PMID 36675056, 2023). "PLS-DA of silicosis patients in our study, further documented the connections between the outcome of silicosis and cytokine predictors: Th1/Th2 pro-inflammatory IL-6, IL-1β and IFN-γ, which were significantly elevated in silicosis patients when compared to controls." (PMID 36311760, 2022). "In silicosis, IL-10 is elevated but has a dual effect: on one side, IL-10 limits the amplitude of the inflammatory response by suppression of the production IL-1β, IL-6 and TNF-α in monocytes and macrophages." (PMID 36672608, 2022). "Similarly, our study found that the secretion of serum TGF-β1, CTGF, TNF-α and IL-6 were higher in patients with silicosis than in healthy subjects." (PMID 35379204, 2022). "As inflammatory cytokines IL-6, IL-1β, TNF-α are also potent inducers of GM-CSF, it is not surprising that these cytokines are strongly associated with each other and act as predictors for silicosis patients." (PMID 36311760, 2022). "Upregulation of cytokines including TNFs,IFN-β precursor, IL-6, atypical chemokine receptor 2, TNFR13BV, and mutantIL-17F may be implicated in the exacerbated, persistent immune response and fibrosisthat occur during the development of silicosis." (PMID 39606764, 2024). "Patientsdiagnosed with complicated silicosis had higher levels of IL-2R, IL-6, IL-8, AAT,ferritin, CRP, and LDH than those diagnosed with simple silicosis." (PMID 39606764, 2024). "Subsequently, these macrophages undergo dysregulated polarization, with secretion of abundant cytokines such as IL-1β, IL-6, TNF-α, and TGF-β1, further promoting inflammation and progression of silicosis." (PMID 39060930, 2024). "RT‒PCR showed that inflammatory cytokines (IL-1β, IL-6 and TNF-α) were upregulated in AMs, but IL-10 expression was not significantly different, which indicated that AMs in the early stage of silicosis were mainly inflammatory macrophages." (PMID 38454505, 2024). "Our previous study suggested that blocking exosome secretion alleviated lung inflammation and decreased the expression of IL-1β, IL-6 and TNF-α in bronchoalveolar lavage fluid in mice with silicosis." (PMID 38454505, 2024). "Among them, IL-1β, IL-6, TNF-α, and TGF-β1 have been identified as key pro-inflammatory and pro-fibrotic cytokines in silicosis." (PMID 39060930, 2024). "In mice, silencing IL-6 receptor-α can ameliorate the secretion of Th2 cytokines (IL-4 and IL-5) and inhibit the activation of the IL-6/JAK/STAT pathway, thereby improving lung function and alleviating the development of silicosis." (PMID 38515835, 2024). "Protein levels of IL-1β, IL-6, and TNF-α increased in the lungs of rats with silicosis and significantly decreased in YCF- and TET-treated rats." (PMID 37381044, 2023). "The secretions of TGF-β1, CTGF, IL-6 and TNF-α in silicosis group were significantly higher than that in control group (p < 0.05)." (PMID 35379204, 2022).
silicosis (continued). "AKEX0011 also significantly decreased the production of inflammatory factors such as TNF-α, IL-1β, IL-6, and TGF-β and the production of fibrosis markers such as collagen I, fibronectin, and α-SMA in silicosis." (PMID 35401236, 2022). "To investigate the possible role of S100A4 in silicosis, we first detected the secretion of S100A4, inflammatory indicator IL-6 and TNF-α, and fibrotic cytokine TGF-β1 and CTGF in the serum of patients with silicosis." (PMID 35379204, 2022). "Western blot showed that the expression levels of IL-1β, IL-6, TNF-α and TGF-β1 in lung tissue from the silicosis group were significantly elevated." (PMID 35959439, 2022). "The secretion of TNF-α, IL-1β, IL-6, TGF-β1, and ox-LDL was significantly higher in the silicosis group than that in the HC group (p < 0.05)." (PMID 32351319, 2020). "The secretion of TNF-α, IL-6, TGF-β1, and ox-LDL was increased in patients with silicosis in comparison to controls, except for IL-1β." (PMID 32351319, 2020). "Miaoet al.30 also found that TNFligand superfamily 4 isoform X1 (TNFSF4), IFN-β precursor, IL-6, atypicalchemokine 2 receptor, and mutant IL-17F were all upregulated in exposed patients,both with and without silicosis." (PMID 39606764, 2024). "The levels of IL-6 are significantly increased in the serum and BALF of patients with silicosis." (PMID 38515835, 2024). "Based on these results, the authors concluded that peripheral blood IL-6 and TNF-α levels are important for silicosis management, and their detection could reduce the number of X-rays as a follow-up procedure." (PMID 36672608, 2022). "IL-6 showed promising results in diagnosing silicosis, including its incipient stage, when opacities are not radiologically visible." (PMID 36672608, 2022). "This hypothesis can be supported by the findings in our study that serum S100A4 levels were positively correlated with TGF-β1 and IL-6, suggested a possible role of S100A4 in inflammation and fibrosis of silicosis." (PMID 35379204, 2022). "In this study, serum levels of S100A4, transforming growth factor-β1 (TGF-β1), connective tissue growth factor (CTGF), interleukin-6 (IL-6) and tumour necrosis factor-α (TNF-α) in patients with silicosis (n = 42) and control group (CG, n = 12) were measured by ELISA." (PMID 35379204, 2022). "Studies found that TNF-α and IL-6 were increased in the serum and BALF of patients with silicosis." (PMID 35379204, 2022). "LDH, alpha 1- antitrypsin, ferritin and CRP showed significant differences between complicated silicosis and exposed and simple silicosis but not between exposed and simple silicosis, and IL-6 showed differences only between complicated and simple silicosis." (PMID 34172787, 2021). "Macrophages play a crucial role in the pathophysiology of silicosis by secreting pro-inflammatory mediators, such as IL-1β, TNF-α, IL-6, MIP-1, and MIP-2, as well as growth factors and fibrogenic mediators, which lead to fibroblast activation and collagen deposition." (PMID 29126438, 2017). "Likewise, patients diagnosed with silicosis showed higher levels of IL-8, AAT, CRP and LDH than exposed patients, and patients diagnosed with complicated silicosis showed higher levels of IL2R, IL-6 IL-8, AAT, ferritin, CRP and LDH than those diagnosed with simple silicosis." (PMID 34172787, 2021). "Therefore IL-6 and IL-23 might not be responsible for the reduction of Th17 in experimental silicosis model." (PMID 22615967, 2012). "Our findings observed that sRAGE were negatively correlated with TNF-α, IL-6, IL-1β, and ox-LDL (indicators of inflammation), but not TGF-β1 (indicator of fibrosis), suggesting that sRAGE might be an anti-inflammatory and not an antifibrotic marker in silicosis." (PMID 32351319, 2020).
Sleep apnea (29 papers, 2010 to 2025). An intermittent cessation of airflow at the mouth and nose during sleep is known as sleep apnea. "Furthermore, a consistent conclusion from another study is that IL-6 levels are associated with both glucose metabolism and sleep apnea." (PMID 39234045, 2024). "This increase in IL-6 levels might be linked to the reduced oxygen consumption observed in sleep apnea patients." (PMID 39234045, 2024). "Sleep apnea episodes can cause hypoxemia and, consequently, an inflammatory state, as the low concentration of oxygen in the arterial blood stimulates the release of IL-6 and TNF-α." (PMID 36102458, 2023). "Others have demonstrated that the increase in TNF-α and IL-6 levels were accompanied by an increase in the AHI in patients with sleep apnea." (PMID 30213594, 2020). "The inflammatory biomarkers CRP and interleukin-6 (IL-6) were found to be elevated in sleep apnea and excessive sleepiness." (PMID 29276708, 2017). "Effective treatment of sleep apnea with continuous positive airway pressure has been shown to decrease the elevated IL-6 serum concentrations." (PMID 26448877, 2015). "Cytokines IL-6 and IL-8 play a significant role in sleep apnea." (PMID 39234045, 2024). "For instance, IL-6 secretion is elevated in sleep apnea, yet estrogen can inhibit IL-6 secretion." (PMID 37215125, 2023). "Sleep-disordered breathing causes widespread inflammation induced by reactive oxygen species (ROS) and inflammatory molecules generated downstream of the nuclear factor kappa B (NFKB) pathway, such as tissue necrosis factor-alpha (TNF-alpha) and interleukin-6 (IL-6)." (PMID 41459054, 2025). "It remains contentious whether treating sleep apnea can influence the levels of IL-6 and IL-8." (PMID 39234045, 2024). "Based on prior evidence for their involvement in the regulation of sleep function and in pro-inflammatory physiology of sleep-disordered breathing, we selected TNF-α, IL-1β, and IL-6, to include as the basic explanatory inflammatory markers in our model." (PMID 23382975, 2013). "Shinji measured the plasma levels of inflammatory factors such as hypersensitive C-reactive protein(hs-CRP), IL-6, and TNF-α in 40 patients with sleep apnea syndrome and found that these inflammatory factor levels were correspondingly elevated in patients with sleep apnea syndrome." (PMID 39799348, 2025). "A recent meta-analysis of 51 studies identified several inflammatory markers that are common in patients with sleep apnea, including elevated serum concentrations of C-Reactive Protein, TNF-α, IL-6, IL-8, intercellular adhesion molecule (ICAM), vascular cell adhesion molecule (VCAM), and selectins." (PMID 26448877, 2015). "That is, numerous inflammatory markers, including IL-6, IL-8, TNF-α, CRP, monocyte chemoattractant protein-1 (MCP-1), ICAM, selectins, VCAM, nitric oxide, and isoprostane, are elevated in body fluids of patients with sleep apnea." (PMID 25873764, 2015). "Moreover, the pro-inflammatory cytokines IL-6 and TNF-α have been suggested to be mediators of excessive sleepiness in humans with pathologic conditions, e.g., sleep apnea and narcolepsy, and in experimentally induced sleepiness, i.e., following sleep deprivation." (PMID 25140521, 2014). "The present investigation is unique in its comprehensive analysis of IL-6, IL-8, IL-10, TNF-α, CRP, and S100B in a single cohort of sleep apnea patients compared to non-OSA controls in both serum and plasma." (PMID 37762178, 2023).
B cell lymphoma (28 papers, 2006 to 2026). "We describe a fundamental and previously unexplored IL-6-dependent mechanistic pathway underlying induction of spontaneous B-cell lymphomas." (PMID 33651821, 2021). "While Eμ-myc mice typically develop B-cell lymphomas at an early age, the loss of IL-6 affects gene expression changes which promote apoptosis or growth arrest in premalignant cells, thereby reducing tumorigenesis." (PMID 33651821, 2021). "Inflammatory markers such as interleukin-6 and C-reactive protein, and apoptotic biomarker, B-cell lymphoma-2 were also measured." (PMID 40893793, 2025). "The activation of the IL-6/hepcidin axis was previously demonstrated in patients with Hodgkin and aggressive B-cell lymphomas." (PMID 37185444, 2023). "LPS induces not only the proliferation and differentiation of mature B cells, but also the secretion of IL-6 in B-cell lymphoma." (PMID 36788460, 2023). "A majority of IL6+/+;Eμ-myc tumors were pro/pre-B cell lymphomas based on their IgM-negative immunophenotype and had a characteristic lymphoblastic morphology." (PMID 33651821, 2021). "We evaluated the contribution of IL-6 in a spontaneous model of B cell lymphoma driven by the Eμ-myc transgene." (PMID 33651821, 2021). "Apart from helper T cells, various cell types of the B cell lymphoma microenvironment are capable of producing the cytokines IL-4, IL-6, IL-10 and TNFα." (PMID 32899476, 2020). "This amplification loop was recently identified in B cells, as B cell-lymphoma with high expression of STAT3 exhibited elevated production of IL-6." (PMID 19284588, 2009). "We also studied two subgroups of PCTs that arose spontaneously in hyperplastic lymph nodes of IL-6-transgenic mice and B-cell lymphomas from iMyc gene-insertion mice." (PMID 17764563, 2007). "For B-cell non-Hodgkin lymphoma, the first line drugs rituximab and bendamustine (RB) increased serum IL-6 more than rituximab and CPA, DOX, vincristine, and prednisone (R-CHOP), and the levels of IL-6 correlated with increased fatigue three months after the end of chemotherapy." (PMID 33352780, 2020). "For B cell lymphoma, IL-6 and IL-10 feedback mediate STAT3 constitutive activation." (PMID 31552035, 2019). "Expression analysis in human B-cell lymphomas showed a positive correlation between IL-6 and IDO1." (PMID 24657910, 2014). "In human B-cell lymphoma IL-6 expression correlated with AHR expression." (PMID 24657910, 2014). "In addition, our data suggest the differential expression of non-coding RNAs that regulate pro-apoptotic pathways may be key to understanding IL-6-mediated survival of MYC-driven B cell lymphoma." (PMID 33651821, 2021). "Chronic antigen stimulation and overproduction of cytokines including cellular IL-6 and IL-10 in the HIV-positive patients also plays a potential role in PEL pathogenesis, similar to what occurs in other non-Hodgkin B cell lymphomas." (PMID 33669719, 2021). "To determine the influence of IL-6 on lymphomagenesis mediated by deregulated MYC expression, we used an Eμ-myc murine model of B cell lymphoma." (PMID 33651821, 2021). "The strong ATA B cell lymphoma stages in mice were CD1d–, LEF-1–, and IL-6+ with increased Arid5a." (PMID 36050343, 2022). "In mouse CD1d– ATA B cell lymphoma, we observed reduced LEF-1 and increased IL-6 and Arid5a." (PMID 36050343, 2022). "TECs releasing IL-6, promoting suppression of PI3K/AKT/mTOR pathway in B-cell lymphoma." (PMID 34095111, 2021). "Initial experiments with copanlisib point to IL6 signaling as a main player in copanlisib resistance; levels of IL6 and phosphorylation of STAT5, Akt, p70S6K, and MAPK were increased in copanlisib-resistant B cell lymphoma cell lines and the resistance was reversible by JAK inhibitor." (PMID 33154951, 2020). "CD137 ligand signals induced secretion of IL-6 and IL-8 specifically in the MM cell lines but not the non MM B cell lymphoma lines." (PMID 20520765, 2010).
B cell lymphoma (continued). "CD137 ligand signaling inhibited proliferation, induced cell cycle arrest and apoptosis and resulted in an increased secretion of IL-6 and IL-8 selectively in MM cell lines but not in non-MM B cell lymphoma cells." (PMID 20520765, 2010). "While it has been demonstrated that TGF-β plus IL-6 promotes TH17 cells in mice, we observed that TGF-β had a suppressive, and not stimulating, effect on TH17 cell differentiation in B-cell NHL, a finding consistent with other previous reports." (PMID 23555036, 2013).
chronic hepatitis (28 papers, 2009 to 2025). An active inflammatory process affecting the liver for more than six months. "The estrogen receptor of hepatocytes has been reported to inhibit the replication and transcription of the hepatitis virus and the release of interleukin-6, a protein associated with chronic hepatitis." (PMID 38555602, 2024). "IL6 correlates positively with risk of HCC in patients with chronic hepatitis." (PMID 35682957, 2022). "For the anti-inflammatory effect of IL-6, a set of studies in animal models involving chronic hepatitis demonstrate that IL-6 signaling is crucial for ameliorating liver injury and fibrosis." (PMID 38890694, 2024). "IL6 expression was reported to be increased in patients with chronic hepatitis, for example following HBV or HCV infection, and also in NASH." (PMID 35682957, 2022). "In patients with CLD, the production of reactive oxygen species and inflammatory cytokines, such as IL-6, increases as chronic hepatitis progresses." (PMID 33798236, 2021). "A causal link has been established between aberrant levels of IL-4 and IL-6 and alcohol-induced hepatitis, primary biliary cirrhosis, and chronic hepatitis in humans." (PMID 31998436, 2020). "For example, IL-6 has been associated with increased HCC risk in chronic hepatitis B38, and adiponectin and IL-6 in chronic hepatitis C39." (PMID 28894136, 2017). "In this study, the major inflammatory cytokines expressed in chronic hepatitis, IL-6 and TNF-α, induced a marked decrease in microRNA-122 (miR-122) levels, and miR-122 expression was downregulated in the livers of chronic hepatitis B (CHB) patients." (PMID 26933995, 2016). "To evaluate the potential effect of IL-6 in CD8+ T cell-mediated chronic hepatitis, we tested the role of IL-6 in the liver inflammation model induced by 2A." (PMID 21394214, 2011). "However, numerous studies in animal models of chronic hepatitis indicate that IL6 signaling can sometimes ameliorate liver injury and fibrosis." (PMID 35682957, 2022). "Furthermore, to investigate whether TNF-α and IL-6 played particularly critical roles in the pathogenesis of chronic hepatitis in the transgenic mice, we neutralized TNF-α and blocked the IL-6 receptor in the livers of these mice." (PMID 23284733, 2012). "In the current study, IL-6 levels were considerably higher in the HCC group, followed by the cirrhotic group, than those in the chronic hepatitis and control groups." (PMID 39071840, 2024). "A study with a relatively small number of cases reported positive correlation between IL-6 levels, transaminase enzymes (ALT, AST), and GGT in patients with chronic hepatitis." (PMID 39596058, 2024). "IL-6 values were significantly higher in the HCC group, followed by the cirrhotic group, than those in chronic hepatitis and control groups (p < 0.001), with a significant correlation with disease activity and progression parameters." (PMID 39071840, 2024). "We also demonstrated that the onset of chronic hepatitis in CN2-29(+/−)/MxCre(+/−) mice was mainly attributable to inflammatory cytokines, (tumor necrosis factor) TNF-α and (interleukin) IL-6." (PMID 23284733, 2012). "As IL-6 and TNF-α are major inflammatory factors in chronic hepatitis, these results suggest that chronic inflammation may contribute to miR-122 downregulation in CHB." (PMID 26933995, 2016). "While in chronic hepatitis, HBV may enhance the expression of IL-6 and IL-6 would in turn promote the production of CRP." (PMID 25874450, 2015).